TMPRSS4 (transmembrane serine protease 4)
Diseases named in the same sentence as TMPRSS4 in open-access papers (continued):
Sharing a sentence is not in itself a finding about the gene and the disease.
tumor (continued). "Reliable antibodies should be developed in order to ascertain the precise location of TMPRSS4 in SCC tumours." (PMID 22067904, 2011). "It is possible that the conditions of the tumour microenvironment switches on TMPRSS4 expression in SCC cells in vivo and that these conditions are not reproduced in in vitro cultures." (PMID 22067904, 2011). "Similarly, overexpression of TMPRSS4, a serine protease expressed on the cell surface that contributes to the degradation of the extracellular matrix, has been suggested to promote tumor proliferation and aggressiveness in BrC." (PMID 40943642, 2025). "Further studies should investigate whether TMPRSS4 promotes tumor initiation in transgenic animal models." (PMID 37009799, 2023). "Moreover, TMPRSS4 serves as a soluble fragment, which is thereby secreted into the tumor environment." (PMID 36380313, 2022). "Moreover, the multivariate analysis revealed that TMPRSS4 and the stages of tumor were also significant prognostic factors for RFS." (PMID 34379296, 2022). "Finally, we explored the relationship between TMPRSS4 and tumor-infiltrated immune cells using TIMER and TISIDB." (PMID 36380313, 2022). "It suggested that there was an intrinsic link between TMPRSS4 and tumor immune infiltration." (PMID 36380313, 2022). "Furthermore, we discovered TMPRSS4 correlated with classical tumor immune cell infiltration (CD4+ T cells, B cells, macrophages, DCs, neutrophils) in TC patients from the TIMER2.0 database." (PMID 36380313, 2022). "TMPRSS4 expression showed strongly positive association with DCs and neutrophils, weakly positive correlation with CD8+ T cells, and negatively correlated with tumor purity, B cells, macrophages." (PMID 36380313, 2022). "We statistically analyzed the IHC score and found that the TMPRSS4 level was strongly correlated with age, tumor size and differentiation, We further evaluated the prognostic significance of TMPRSS4 expression by employing univariable and multivariable Cox proportional hazards analysis." (PMID 33816264, 2021). "In addition, TMPRSS4 promoted resistance to anoikis, thereby increasing survival of circulating tumor cells and promoting early metastasis." (PMID 34809669, 2021). "Further studies should investigate whether TMPRSS4 promotes tumor initiation using transgenic mouse models." (PMID 34809669, 2021). "TMPRSS4 suppression in the 22Rv1 xenograft model significantly decreased tumor growth." (PMID 34809669, 2021). "Moreover, overexpression of TMPRSS4 is positively correlated with tumor size and differentiation, also a reduced overall survival rate." (PMID 33816264, 2021). "The results show that the higher TMPRSS4 expression indicates the lower tumor stage." (PMID 32695668, 2020). "In conclusion, our study first identified CORO1C and TMPRSS4 as vital regulators in the process of tumor progression through influencing EMT and could be developed to effective prognostic and therapeutic targets in future BC treatment." (PMID 32695668, 2020). "Furthermore, clinically relevant genes that are associated with tumor growth such as VIM, ITGB1, FOXQ1, FN1, MSN, CXCL and TMPRSS4 were also downregulated." (PMID 32784836, 2020). "As TMPRSS4 expression is epigenetically regulated, methylation status could be used in circulating tumor DNA from liquid biopsies to monitor patients." (PMID 31817025, 2019). "In vivo studies have also shown that TMPRSS4 increases subcutaneous tumor growth and metastasis." (PMID 31659178, 2019). "We previously showed in animal models that abrogation of TMPRSS4 using short hairpin RNA (shRNA) strategies impedes tumor homing and growth, suggesting that targeting this protein in NSCLC may result in a strong therapeutic effect." (PMID 31817025, 2019). "The median H-score was used to categorize patients in high vs. low TMPRSS4 tumor expression." (PMID 31817025, 2019). "TMPRSS4 mediates tumor cell invasion, migration, and metastasis." (PMID 28678795, 2017).
tumor (continued). "On the other hand, it is not well established whether, and if so, by which mechanisms, TMPRSS4 modulates tumor cell proliferation." (PMID 27385093, 2016). "However, further studies analyzing specific tumor types and perspectives are needed to further verify the clinical significance of TMPRSS4 expression in solid tumors." (PMID 27344186, 2016). "Potential roles of TMPRSS4 in tumor cell proliferation and invasion were further explored." (PMID 27385093, 2016). "However, up to now, no meta-analyses have been performed to evaluate the prognostic value of TMPRSS4 expression in the tumor patients." (PMID 27344186, 2016). "Previously, we demonstrated that TMPRSS4 mediates tumor cell invasion, migration, and metastasis." (PMID 27385093, 2016). "The protumorigenic and prometastatic role of TMPRSS4 described in experimental models may influence tumor features leading to worse clinical outcome." (PMID 26989022, 2016). "Five weeks after orthotopic inoculation of Lv-GFP or Lv-TMPRSS4 tumor tissue into the liver, some of the mice were sacrificed and metastases were evaluated by luminescence imaging system and pathological examination, the other mice were left for evaluation of survival time." (PMID 26190376, 2015). "Since the hypoxic conditions that commonly prevail in the tumor microenvironment are known to modulate gene expression, TMPRSS4 protein expression was evaluated under normoxic and hypoxic conditions in two tumor cell lines positive for TMPRSS4 mRNA (H358 and H596)." (PMID 22692880, 2012). "In addition, our findings suggest that expression of TMPRSS4 in the tumor microenvironment is regulated by hypoxia." (PMID 22692880, 2012). "No results from normal lung were available for any of the databases and only comparisons between TMPRSS4 expression in both the types of tumour histologies could be performed." (PMID 22067904, 2011). "Alternatively, stromal cells within the squamous tumour may be responsible for TMPRSS4 expression, instead of tumour cells themselves." (PMID 22067904, 2011). "Furthermore, we show that TMPRSS4 is highly expressed in tumours compared with the normal lungs, with a higher expression in SCC than in AC." (PMID 22067904, 2011). "In addition, TMPRSS4 may be involved in regulating the tumor microenvironment (e.g., regulating the immune status or angiogenesis) via NF-κB, thereby contributing to malignancy; again, these possibilities require further investigation." (PMID 37009799, 2023). "Furthermore, we analyzed its prognostic value from Kaplan-Meier Plotter database, and the relationship between TMPRSS4 and the abundance of tumor-infiltrating lymphocytes (TILs) in TC in TISIDB, screening potential immune targets to explore novel mechanisms for the clinical management of TC." (PMID 36380313, 2022). "Moreover, our study offers insights into a novel mechanism by which TMPRSS4 may affect the clinical outcome of TC through tumor immune infiltration but also paves the way for further studies on immunotherapy against TC." (PMID 36380313, 2022). "Thus, TMPRSS4/SLUG–TWIST1/SOX2 axis may represent a novel mechanism involved in the control of tumor progression." (PMID 34809669, 2021). "In addition, it is possible that TMPRSS4 may be involved in the regulation of the tumor microenvironment, such as immune regulation or angiogenesis, via NF-κB to contribute to the accelerated development of aggressive malignancy." (PMID 31292507, 2019). "The fact that TMPRSS4 expression is epigenetically regulated by DNA methylation suggests that methylation status could be used as a biomarker in liquid biopsy through analysis of circulating tumor (ct)DNA." (PMID 31817025, 2019). "Interestingly, the 5-gene classifier contained only genes labeled related to activated stroma (POSTN) and basal-like tumor (AHNAK2, SERPINB5, TMPRSS4), and excluded classical tumor-like genes, which might explain the inferior classification performance." (PMID 29675033, 2018).
tumor (continued). "However, protein levels were increased under hypoxic culture conditions suggesting that hypoxia within the tumor microenvironment may upregulate TMPRSS4 protein expression in vivo." (PMID 22692880, 2012). "Eleven potential tumor targets were identified, including CEACAM5, TMPRSS4, COL17A1, CLDN18, and AQP5." (PMID 40379788, 2025). "Given the complex tumor microenvironment (TME), we further investigated the prognostic predictive role of TMPRSS4 in different lymphocyte-enriched THCA patients." (PMID 36380313, 2022). "Taken together, these data describe tumor- and lung-pertinent expression patterns of the major SARS-CoV-2 receptor ACE2 and priming proteases TMPRSS2 and TMPRSS4 in LUAD patients." (PMID 33809063, 2021). "We conclude from our study that TMPRSS4 is an independent prognostic indicator of reduced RFS and OS in early NSCLC, and that TMPRSS4meth status differentiates between tumor-free individuals and those with NSCLC." (PMID 31817025, 2019). "We then examined the anti-tumor activity of KRT1853 and IMD-0354 in nude mice bearing TMPRSS4-overexpressing DU145 xenografts." (PMID 31292507, 2019). "Another meta-analysis approach based on PDAC datasets allowed the identification of a 5 genes classifier signature (TMPRSS4, AHNAK2, POSTN, ECT2, SERPINB5) with 95% sensitivity and 89% specificity in discriminating PDAC from non-tumor samples." (PMID 30236127, 2018). "In conclusion, TMPRSS4 is a novel independent prognostic biomarker regulated by epigenetic changes in SCC and a potential therapeutic target in this tumor type, where targeted therapy is still underdeveloped." (PMID 26989022, 2016). "Other tumor promoter genes described in NSCLC, such as ELMO3 and 14-3-3s, show similar patterns of promoter methylation/expression to those observed for TMPRSS4." (PMID 26989022, 2016). "Therefore, we conclude that TMPRSS4 promoter is methylated in normal lung, whereas an abnormal hypomethylation occurs in tumors, which could constitute an oncogenic mechanism, as described for other tumor promoting genes." (PMID 26989022, 2016). "More over, we found that overexpression of TMPRSS4 also significantly suppressed the expression of RECK, together with increased tumor angiogenesis, through activating ERK1/2 pathway." (PMID 26190376, 2015). "We demonstrate, for the first time, TMPRSS4 remarkably suppresses the expression of RECK, an inhibitor of angiogenesis, drastically induces tumor angiogenesis." (PMID 26190376, 2015). "Several genes, such as TMPRSS4, STAR, ST7L, HAS3, FGFR3, CASZ1 and HR, were found to have gene expression changes at the very earliest stages of tumor thickening." (PMID 18442402, 2008). "This “non-basal-like non-classical” tumor subset expresses core signatures such as high TMPRSS4, SLC6A14, IFI27, CST1, and STYK1." (PMID 39774001, 2025). "The expression of TMPRSS4 was positively and significantly correlated with the depth of tumor invasion (T) and venous invasion (v), but not with the age, gender, tumor size, lymph node metastasis (N), histological type, and stages of the tumor." (PMID 34379296, 2022). "In addition, we developed a robust ddPCR method to quantify CpG methylation levels within the TMPRSS4 and SHOX2 promoters in blood and BAL that can differentiate between NSCLC patients and tumor-free individuals." (PMID 31817025, 2019). "A 5-gene PDAC classifier (TMPRSS4, AHNAK2, POSTN, ECT2, SERPINB5) achieved on average 95% sensitivity and 89% specificity in discriminating PDAC from non-tumor samples in four training sets and similar performance (sensitivity = 94%, specificity = 89.6%) in five independent validation datasets." (PMID 26993610, 2016). "In addition, we demonstrated that TMPRSS4 remarkably suppressed the expression of RECK, an inhibitor of angiogenesis, and drastically induced tumor angiogenesis and growth." (PMID 26190376, 2015).
tumor (continued). "The present findings also identify link between TMPRSS4 and RECK that may enhance our understanding of tumor angiogenesis and lead to the development of novel treatment strategies." (PMID 26190376, 2015). "TMPRSS4 expression did not correlate with sex, tumor location, differentiation, or histological classification (P>0.05)." (PMID 23922976, 2013). "A role for human TMPRSS4 interaction with eNaC in the tumor microenvironment has not been explored and represents an intriguing possibility." (PMID 22692880, 2012). "The absence of detectable TMPRSS4 protein in tumor lines with high levels of mRNA suggested the involvement of environmental factors in the control of mRNA translation." (PMID 22692880, 2012). "Expression of TMPRSS4 showed a >30-fold increase (P<0.001) in tumours in comparison with non-malignant samples." (PMID 22067904, 2011). "However, the multivariate analysis revealed that the stages of tumor and venous invasion were significant prognostic factors for OS, but TMPRSS4 was not a significant prognostic factor for OS." (PMID 34379296, 2022). "We found TMPRSS4-overexpression HCC cells formed much bigger tumors in the anterior chamber of mice (yellow arrow) with large amounts of angiogenesis induced (white arrow), which could contribute to tumor growth." (PMID 26190376, 2015).
infection (20 papers, 2011 to 2024). The state of being infected such as from the introduction of a foreign agent such as serum, vaccine, antigenic substance or organism. "Loci exhibiting the strongest stimulation by infection and repression by remdesivir included several proteases (TMPRSS4, TMPRSS6, TMPRSS11D, TMPRSS11E) closely related to TMPRSS2, a host factor during SARS-CoV-2 receptor-mediated endocytosis." (PMID 37205380, 2023). "For example, TMPRSS2 and TMPRSS4 mRNAs were more abundant in Caco-2 cells than A549 cells, but the infection was more pronounced in A549." (PMID 34064066, 2021). "who reported that TMPRSS4 besides TMPRSS2 enhances infection of small intestinal enterocytes with SARS-CoV-239." (PMID 33293627, 2020). "Both wild-type and Tmprss4−/− mice lost weight after infection, with comparable kinetics, and showed similar survival rates." (PMID 26889029, 2016). "Different expression patterns of TMPRSS2 and TMPRSS4 in bat airway organoids might affect the infection of different bat species." (PMID 36916937, 2023). "TMPRSS4 has been linked with SARS-COV-2 cell entry and infection of several host cell types." (PMID 34078171, 2021). "Moreover, we recently demonstrated that in Tmprss2−/− Tmprss4−/− double knock-out mice, replication and pathology after infection with our H3N2 isolate was strongly diminished and infected mice survived." (PMID 30084768, 2018). "Deletion of Tmprss4 alone in knockout mice does not protect them from body weight loss and death upon infection with H3N2 influenza virus." (PMID 26889029, 2016). "At 24 h post-infection, total RNA was isolated and the mRNA expression of TMPRSS2 and the related protease TMPRSS4 was determined by RT–qPCR." (PMID 37208193, 2023). "TMPRSS2 and TMPRSS4 have been demonstrated to be important for cleavage of SARS-CoV-2 to allow entry and infection of host cells." (PMID 34051791, 2021). "To determine the function of TMPRSS serine proteases in facilitating SARS-CoV-2 S mediated infection of primary human IECs, we used CRISPR/Cas9 gene editing to deplete TMPRSS2 or TMPRSS4 expression in human duodenum enteroids." (PMID 32404436, 2020). "Higher ACE2 levels correlated with infection although TMPRSS2 and TMPRSS4 expression also showed a positive correlation as well." (PMID 32404436, 2020). "Three days after infection with lentiviruses, over 80% of the transduced cells (Lv-GFP group and Lv-TMPRSS4 group) showed green fluorescence under the fluorescence microscope." (PMID 26190376, 2015). "At 72 h post infection (hpi), the different levels of rTS-2B/GFP titers from the cells expressing proteases were observed in the order of Tmprss9 > Cfd > Prss23 = Tmprss4 > F7 > ev, and those of rTS-GFP titers were observed in the order of Tmprss9 > Tmprss4 > F7 > ev = Cfd = Prss23." (PMID 37042750, 2023). "ACE2 as well as Fas‐L (Fas‐Ligand) and TMPRSS4 (transmembrane serine protease 4), two additional genes involved in the infection process of SARS‐CoV‐2 were not expressed neither in AD‐MSCs, WJ‐MSCs nor in BM‐MSCs." (PMID 34821008, 2022). "Indeed, TMPRSS4 expression did not affect virus binding at 4°C, but led to an increase in infection as evidenced by enhanced viral gene transcription 1 hour post warming cells to 37°C." (PMID 32404436, 2020). "Infection sensitivities of various cell types did not correlate with mRNA abundance of hACE2, TMPRSS2, or TMPRSS4." (PMID 34064066, 2021). "Note that the lack of correlation of hACE2 mRNA with infection of different cell types was not due to the abundance of TMPRSS2 and TMPRSS4, which prime SASR-CoV-2 spike proteins for hACE2-dependent viral entry." (PMID 34064066, 2021).
adenocarcinoma (3 papers, 2012 to 2021). A common cancer characterized by the presence of malignant glandular cells. "At the transcriptional level, TMPRSS4 message was significantly elevated in the majority of human squamous cell and adenocarcinomas compared with normal lung tissues." (PMID 22692880, 2012).
GI tumors (1 paper, 2022). "There was also significant positive correlation of TRIM31 with TMPRSS2 and TMPRSS4 gene pair in all GI tumor samples." (PMID 35970857, 2022). "As TMPRSS2 and TMPRSS4 gene expression is positively correlated in both GI tumors and cell lines, we initially investigated whether there is an additional number of genes which are commonly associated with TMPRSS2 and TMPRSS4 genes in GI cancer cell lines." (PMID 35970857, 2022). "Among these, TMPRSS2 and TMPRSS4 was commonly observed in all gastrointestinal tumor types." (PMID 35970857, 2022). "We therefore characterized the expression profiles of a number of genes involved in SARS-CoV-2 infection pathway and found higher ACE2, TMPRSS2, TMPRSS4, SCARB1, CTSL and NRP1 expression in all GI tumor samples relative to their normal counterparts." (PMID 35970857, 2022). "Importantly, all gastrointestinal tumor samples showed a positive correlation between TMPRSS2 and TMPRSS4 genes." (PMID 35970857, 2022).
TMPRSS4 also shares sentences with these, for which no sentence is quoted: pancreatic ductal adenocarcinoma (3 papers); CNS cancer (2); colon adenocarcinoma (2); liver cancer (2); ovarian cancer (2); asthma (1); basal cell carcinoma (1); carcinoid (1); cervical cancer (1); Cirrhosis (1); Ewing sarcoma (1); fibrosis (1); glioma (1); hyperlipidaemia (1); idiopathic pulmonary fibrosis (1); kidney cancer (1); lung (1); melanoma (1); metastatic cancers (1); metastatic disease (1); metastatic melanoma (1); neurological disorders (1); pancreatic adenocarcinoma (1); rectal adenocarcinoma (1); stomach adenocarcinoma (1); stomach cancer (1); thyroid neoplasm (1).